CCR2 (C-C motif chemokine receptor 2)
Diseases named in the same sentence as CCR2 in open-access papers (continued):
Sharing a sentence is not in itself a finding about the gene and the disease.
infectious disease (9 papers, 2012 to 2025). A disorder directly resulting from the presence and activity of a microbial, viral, or parasitic agent in humans. "The importance of monocyte recruitment in limiting the progression of infectious diseases has been most clearly demonstrated in CCR2 deficient (CCR2−/−) mice." (PMID 23094119, 2012). "Besides IBD, CCR2+ pro-inflammatory intestinal macrophages are also increased in infectious disease mouse models, where they have been linked to beneficial responses in host defense." (PMID 37400850, 2023). "To address this issue, we used recipient mice reconstituted by BM cells derived from CCR2 KO mice that are monocytopenic, in which tissue recruitment of monocytes is impaired in infectious disease models." (PMID 26626303, 2015). "Chetomin was identified as the first naturally-occurring antagonist of the C-C chemokine receptor type 2 (CCR2), known for the involvement in inflammatory processes and infectious diseases." (PMID 31569621, 2019). "Single nucleotide polymorphisms (SNPs) found in CCL2 and CCL5 gene (chromosome 17), in CCR2 and CCR5 gene (chromosome 3) have been related to infectious diseases including West Nile virus, dengue, HIV24,25, Hepatitis C26 and tuberculosis." (PMID 29057937, 2017).
cardiac disease (7 papers, 2018 to 2024). "This was associated with a palpable increase in the number of CCR2+ cells in the hearts of patients with ACM compared with hearts of age-matched controls with no history of heart disease." (PMID 38564300, 2024). "In contrast, chronically infected subjects with no signs of cardiac dysfunction had CD14hiCD16– and CD14hi CD16+ monocyte subsets with higher CCR2 expression than those found in patients with severe cardiac disease and in the uninfected healthy controls, respectively." (PMID 30346948, 2018). "CCL2 receptor (CCR2), transcript levels were significantly increased at four weeks of BPA, even before the onset of clinical manifestation of heart disease, and remained elevated after 16 weeks of BPA." (PMID 32144343, 2020). "Third, MHCII+CCR2+ macrophages accompanied by inflammatory monocyte infiltration occurred later, and the number was not as large as that in other cardiac disease models, representing a delayed and relatively mild inflammation." (PMID 38601160, 2024). "However, when the expression of IL-6, MCP-1, and CCR2 was evaluated, we found that only PBMC from patients with heart disease displayed significantly increased levels of these cytokines in comparison with healthy individuals." (PMID 35360222, 2021).
liver (6 papers, 2014 to 2025). "We have detected CD11b+CCR2+Trem2high monocytes in both liver NPCs and blood, which were increased by liver IR." (PMID 41510234, 2025).
peripheral neuropathy (6 papers, 2016 to 2022). A disorder affecting the peripheral nervous system. "Elevated Ccr2 and Ccl2 expression have been previously observed in the dorsal root ganglia following the administration of another anticancer agent, paclitaxel, and this was positively correlated with peripheral neuropathy." (PMID 30906773, 2019). "Also, we demonstrated the necessity of TLR4 in both male and female migratory responses similar to other studies showing that TLR4 signaling is critical for CCR2-dependent monocyte migration through binding of MCP1 to CCR2 in LPS studies, in angiogenesis and peripheral neuropathy." (PMID 35422759, 2022).
colon (4 papers, 2019 to 2025). "During chronic inflammation, CCR2+ BM-derived monocyte and fibrocyte infiltration into the colon and CC chemokine ligand 2 production increased, leading to colon fibrosis in EGFP BM chimeras." (PMID 31189971, 2019). "In inflamed colons, the recruitment of inflammatory monocytes to the LP is facilitated through CCR2, followed by their subsequent migration to the MLN, indicating colon inflammation." (PMID 38239365, 2023).
adenocarcinoma (3 papers, 2020 to 2022). A common cancer characterized by the presence of malignant glandular cells. "Conclusively, these data indicated that HFD‐induced dysbiosis accelerated intestinal adenoma‐adenocarcinoma sequence through activation of MCP‐1/CCR2 axis, which would provide new insight into better understanding of the mechanisms and prevention for HFD‐related CRC." (PMID 31957197, 2020). "In a follow-up study, targeting pSTAT3–CCL2 signaling with C-C chemokine receptor type 2 (CCR2) antagonists reversed the ADT induced cell invasion and macrophage infiltration in transgenic adenocarcinoma of the mouse prostate-C1 (TRAMP-C1) mouse tumors." (PMID 32754615, 2020).
immune diseases (3 papers, 2018 to 2024). "CC chemokine receptor 2 (CCR2) has been linked to many inflammatory and immune diseases, making it a relevant drug target." (PMID 39201670, 2024). "The MCP-1/CCR2 signaling axis has been implicated in the trafficking of T cells, macrophages, and myeloid-derived suppressor cells in tumors and immune disorders." (PMID 29523215, 2018). "Targeting CCL2–CCR2 axis has shown a good outcome in mouse models, but anti-CCL2 mAbs or CCR2 antagonists are mainly used to treat immune diseases in the clinical trials." (PMID 36246629, 2022).
blood cancer (2 papers, 2021 to 2024). "Thus, there is evidence for the role of the CCL2/CCR2 axis in blood cancers." (PMID 34804061, 2021).
brain diseases (2 papers, 2019 to 2020). "Our data implicate reduced blood-brain barrier degradation in Ccr2-deficient mice, which has previously been demonstrated in other brain diseases." (PMID 32668709, 2020).
gynecological tumor (1 paper, 2022). "Consequently, CCL2/CCR2 axis can also be further studied as a new target for gynecological tumor therapy." (PMID 36403055, 2022).
head and neck tumors (1 paper, 2025). "Among the key genes, only CCR2 expression showed a significant association, with high expression levels linked to improved OS, highlighting its potential prognostic value in head and neck tumors." (PMID 40061903, 2025). "Clinically, high CCR2 expression correlates with prolonged overall survival in head and neck tumor patients." (PMID 40061903, 2025). "Notably, the expression levels of CCR2, along with miR-142, miR-146a, and miR-223, were identified as prognostically relevant in patients suffering from head and neck tumor." (PMID 40061903, 2025).
heart (1 paper, 2021). "Nevertheless a distinct contribution of macrophage subsets to the outcome of lymphatic remodeling was provided by CCR2 antagonist treatment that preserved cardiac macrophage subsets ratio and reduced lymphatic remodeling within the hypertrophic heart." (PMID 34413352, 2021).
hematological malignancies (1 paper, 2025). "Monocyte chemoattractants, such as C-C motif chemokine ligand 2 (CCL2) and its homologous receptor C-C chemokine receptor type 2 (CCR2), are targeted for the treatment of solid tumors and hematological malignancies using monoclonal antibodies and receptor antagonists." (PMID 40302816, 2025).
musculoskeletal disease (1 paper, 2017). "For these experiments, WT and CCR2-DTR mice were administered DT at day -1 and day +2 relative to virus inoculation and mice were monitored for 10 days, the peak of the acute disease phase, for effects on weight gain and for the development of virus-induced musculoskeletal disease signs." (PMID 29244871, 2017). "In addition, CHIKV-induced musculoskeletal disease was more severe in Ccr2-/- mice, which displayed diminished recruitment of monocytes and enhanced recruitment of neutrophils to tissues, suggesting that monocytes may protect from more severe forms of CHIKV-induced musculoskeletal disease." (PMID 29244871, 2017).
vasculopathy (1 paper, 2010). "We have detected significant local reductions in inflammatory cell responses and vasculopathy development with either GAG or CCR2 deficiency or after treatment with viral chemokine modulating proteins (CMPs) targeting GAG or receptor binding." (PMID 20463901, 2010). "Donor tissue GAG or CCR2 deficiency markedly reduced inflammation and vasculopathy, whereas recipient deficiencies did not." (PMID 20463901, 2010). "M-T1 and M3 inhibited WT (Ccr2+/+ and Ndst1+/+, p≤0.006) allograft vasculopathy, but did not block vasculopathy in Ccr2−/− (p = 0.61)." (PMID 20463901, 2010).
CCR2 also shares sentences with these, for which no sentence is quoted: Duchenne muscular dystrophy (5 papers); head and neck cancer (4); Allergy (3); delirium (3); Encephalopathy (3); esophageal cancer (3); glaucoma (3); nasopharyngeal carcinoma (3); non-alcoholic fatty liver disease (3); Osteopenia (3); retinopathy (3); acne (2); acute lung injury (2); acute promyelocytic leukemia (2); AIDS dementia (2); Anorexia (2); carotid atherosclerosis (2); cholangitis (2); chronic cystitis (2); chronic hepatitis (2); chronic hepatitis B (2); Chronic Lymphocytic Leukemia (2); metastasis (2); myocardial ischemia (2); non-Hodgkin lymphoma (2); peripheral artery disease (2); polyarthritis (2); renal failure (2); sarcopenia (2); schizophrenia (2).
A further 119 diseases each share a sentence with CCR2 in 2 papers or fewer.